PTCH1 (patched 1)
Diseases named in the same sentence as PTCH1 in open-access papers (continued):
Sharing a sentence is not in itself a finding about the gene and the disease.
medulloblastoma (continued). "Moreover, terminal deoxynucleotidyl transferase-mediated biotinylated UTP nick end labeling (TUNEL) staining showed that GADD34 mutation, either heterozygous or homozygous, did not significantly alter cell apoptosis in medulloblastoma in Ptch1+/− mice." (PMID 27802424, 2016). "The genetic aberrations in the two patients with a history of medulloblastoma were one patient with BRCA1-splice site 4987-1 G>A, which corresponds to the splice acceptor site near to C-terminus and a second patient with two different alterations in the PTCH-1 gene, N97fs*43 and K163fs*6." (PMID 25859559, 2015). "Similarly, over-expression of associated network clusters enriched for SHH pathway members, GLI1, PTCH1 and PTCH2, was exclusive to human SHH medulloblastoma, and expression levels were significantly higher than in CD133+ NSCs, NPCs and all other controls used in this study." (PMID 25412507, 2014). "After siRNA-mediated GLI1 silencing in Daoy and U87MG cell lines, expression of PTCH1 decreased, compared with scrambled siRNA-transfected and untransfected cell lines, which may suggest positive regulation of PTCH1 by GLI1 in medulloblastomas and astrocytomas." (PMID 21059263, 2010). "Meanwhile, both ligand-dependent (co-expression of IHH-PTCH1) and independent inhibitors (SMO; PTCH1; GLI) may be considered as effective Hh signaling inhibitors in OS, while their effects has been shown in many cancers such as basal cell carcinoma and medulloblastoma." (PMID 30349420, 2018). "The implied likelihood of developing medulloblastoma for both ELP1 and particularly GPR161 are overall quite low and at or well below that of PTCH1 for which no screening in childhood for medulloblastoma is recommended." (PMID 36961676, 2023). "CD1d, CD38, and CD81 showed interesting expression profiles in the primary screen but have not been identified as markers of medulloblastoma and so they, along with CD117’s low expression in Ptch1 deleted cells, were not further investigated in this study." (PMID 30657775, 2019). "The most common gene expression outlier in nonhematopoietic tumors was PTCH1 (OMIM 601309), overexpressed in 11 samples from craniopharyngioma, neurofibroma, sarcoma, glioma, medulloblastoma, and osteosarcoma." (PMID 31651965, 2019).
basal cell carcinoma (105 papers, 2006 to 2026). A carcinoma involving the basal cells. "Somatic testing arranged on three basal cell carcinomas identified a common PTCH1 frameshift variant, which on manual re-analysis of peripheral blood DNA was present at < < 1% VAF." (PMID 41888819, 2026). "Loss-of-function mutations in the Patched-1 (PTCH1) gene are found in approximately 70% to 75% of basal cell carcinoma (BCC) cases." (PMID 38534742, 2024). "The result shows that the presence of the PTCH1 somatic mutation increases the magnitude of the differential expression of genes in the “basal cell carcinoma pathway” and “hedgehog pathway” in both low and high As exposure groups." (PMID 38920684, 2024). "This shows a significant association (interaction p = 2.48 × 10−17) between PTCH1 mutation status and the overexpression of the “basal cell carcinoma pathway”." (PMID 38920684, 2024). "This study aimed to analyze the possible association between PTCH1 gene variants (rs357564, rs2236405, rs2297086, and rs41313327), mRNA, and protein expression in patients with basal cell carcinoma from western Mexico." (PMID 38287479, 2024). "The recommendations for PTCH1 mutation carriers are annual basal cell carcinoma screening at age 10, a baseline echocardiogram to be performed during infancy, as well as dental exams with a concurrent jaw X-ray every 12-18 months beginning in childhood." (PMID 37090309, 2023). "Loss-of-function mutations of tumor suppressor gene patched homolog 1 (PTCH1) occur in 30 ~ 40% of basal cell carcinomas." (PMID 36209184, 2022). "Since approximately 85% of basal cell carcinomas display mutations in the Shh pathway and around 73% of those are attributed to a mutation in Ptch1, the role of SNAP29 in basal cell carcinoma should be further investigated." (PMID 34069872, 2021). "A mutation in Ptch1 facilitates a permanent activation of the Shh pathway and is associated with basal cell carcinoma." (PMID 34069872, 2021). "Alterations in PTCH1 gene were associated with the basal cell carcinoma and basal cell nevus syndrome." (PMID 33127962, 2020). "Previous studies have demonstrated that loss of function mutations of the tumor suppressor PTCH1 or gain of function mutations of SMO are associated with basal cell carcinoma." (PMID 32784501, 2020). "The first goal of this study was to explore changes in gene expression that can be attributed to mutations in PTCH1 and can possibly contribute to molecular abnormalities of basal cell carcinomas." (PMID 30858923, 2019). "Aberrant activation of the Hedgehog pathway represents the molecular driver in basal cell carcinoma pathogenesis, with the majority of BCCs carrying somatic point mutations, mainly ultraviolet (UV)-induced, and/or copy-loss of heterozygosis in the PTCH1 gene." (PMID 29165358, 2017). "PTCH1 A563 was mutated in one colorectal cancer (p.A563T; c1687G>A), a lung adenocarcinoma (p.A563S; c1687G>T) and in a basal cell carcinoma (p.A563V; c1688C>T)." (PMID 24368541, 2013). "Type I HH pathway activation includes gain-of-function mutations in SHH that contribute to the formation of basal cell carcinoma, and heterozygous loss-of-function mutations in PTCH1 which cause Gorlin syndrome, basal cell cancers, and a range of other neoplasms including medulloblastoma." (PMID 36986819, 2023). "Furthermore, PTCH1 mutations have also been linked to the promotion of distant metastasis and recurrence in basal cell carcinoma." (PMID 37533228, 2023). "Since PTCH1 functions as a tumor suppressor, Danaee and colleagues have found that loss of PTCH1 function due to mutation or deletion contributed to the genesis of basal cell carcinoma." (PMID 24073265, 2013). "Because loss-of-function mutations in the tumor suppressor PTCH1 cause elevated GLI1 expression in a large proportion of basal cell carcinomas, we tested whether the P681L mutation altered PTCH1 function." (PMID 24368541, 2013).
basal cell carcinoma (continued). "Interestingly, the tumor with the highest level of GLI1 expression (tumor ID TCGA-AA-3715) harbored a missense mutation in PTCH1 (P681L; c.2042C>T) that was identical to a confirmed somatic alteration previously identified in a basal cell carcinoma." (PMID 24368541, 2013). "A recent study has reported that certain haplotypes of PTCH1 polymorphisms may mediate the susceptibility to basal cell carcinomas." (PMID 19032739, 2008). "Interestingly, human MBs and basal cell carcinomas (BCCs) are frequently ciliated and abnormal activation of canonical HH signaling, through loss of the HH receptor PTCH1 or activation of SMO, is frequently found in human patients and is sufficient to induce these tumors in mice." (PMID 34638386, 2021). "Its constitutive activity is suppressed by the 12-transmembrane (12TM) protein PTCH1 and numerous small molecule antagonists including the approved antineoplastic (basal cell carcinoma) drug Vismodegib." (PMID 39713355, 2024). "Inactivating mutations of PTCH1 and SMO, occur in 90% and 10%, respectively of basal cell carcinoma." (PMID 37013122, 2023). "The PTCH1 p.P1315L mutation has also been identified in solitary OOC and reported to be unrelated to the risk of basal cell carcinoma, which is one of the symptoms of NBCCS." (PMID 36242048, 2022). "Dysfunctional PTCH1 causes constitutive activation of smoothened (SMO), resulting in continuous activation of hedgehog signaling and its target genes in basal cell carcinoma, making SMO a promising target." (PMID 36209184, 2022). "Inactivating mutations in PTCH1 and activating mutations in SMO have been detected in 73% or 20%, respectively, of patients with basal cell carcinoma (BCC), a stem cell-based malignancy accounting for ~90% of all solid tumors." (PMID 34518642, 2021). "Early events of basal cell carcinoma (BCC) tumorigenesis are triggered by inappropriate activation of SHH signaling, via the loss of Patched1 (Ptch1) or by activating mutations of Smoothened (Smo)." (PMID 31963474, 2020). "Basal cell carcinoma (BCC) is the most common human cancer, characterized by aberrant activation of the hedgehog (HH) signaling pathway resulting from mutations in the patched 1 (PTCH1) or smoothened (SMO) genes." (PMID 31756206, 2019). "Somatic mutations in the components of Hh signaling (PTCH1 and SMO) have been shown to be a major cause of basal cell carcinoma, and dozens of Hh inhibitors have been developed." (PMID 31775795, 2019). "The results of the present study also showed that the expression of GLI1, SHH, and PTCH1 involved in the basal cell carcinoma pathway was up-regulated in short-hair rabbits." (PMID 30770723, 2019). "In the case of basal cell carcinoma (BCC), Hh dysregulation is driven by a mutations in the PTCH1 gene, which blocks its ability to repress SMO." (PMID 30379908, 2018). "Pathways that followed were ligand-receptor interactions (IHH, PTCH1) (p-value = 5.76 × 10−5) and signalling in basal cell carcinoma (BMP2, STK36, PTCH1) (p-value = 6.73 × 10−5)." (PMID 28117334, 2017). "Individuals with NBCCS have PTCH1 mutations and presents clinically with multiple and recurrent KCOT as well as other neoplasms (e.g. basal cell carcinoma)." (PMID 27066764, 2016). "PTCH1 plays a role in the hedgehog pathway, and dysregulations of this pathway are known to be crucial for the carcinogenesis of many types of cancers including sporadic as well as hereditary basal cell carcinoma." (PMID 36233269, 2022). "In addition, oncogenic markers typical of basal cell carcinoma (Gli-1, Gli-2, Ptch-1, n = 2 cases) and melanoma (c-kit, MAGE, CDK4, n = 1) were markedly upregulated in skin lesions." (PMID 33509032, 2021). "rs357564 is a missense variant within PTCH1 and rs1529889 is an intronic variant within ADAMST17. rs357564 is predicted to be ‘functional’ by the prediction tool FATHMM and was reported to be associated with oral clefts, basal cell carcinoma and ameloblastoma." (PMID 27591082, 2017).
basal cell carcinoma (continued). "Pedigrees with multiple or early-onset basal cell carcinomas without other features of the disease did not test positive for PTCH1 mutations." (PMID 19032739, 2008). "In addition to those that are potential germline polymorphisms, we found three SMO missense mutations, and one PTCH1 frameshift mutation that are novel and have not been documented in basal cell carcinoma." (PMID 23349881, 2013). "Our observation in colorectal tumors of two PTCH1 mutations, P681L and A563T/A563V, that have also been found in basal cell carcinomas suggests the existence of a small but perhaps not insignificant subset of colorectal tumors that grow in response to autocrine Hh signaling." (PMID 24368541, 2013). "In the basal cell carcinoma pathway, 11 up-regulated genes, including GLI1, PTCH1, and SHH, were identified." (PMID 30770723, 2019). "The second proband, a 39-year-old female with a history of > 250 basal cell carcinomas, had previously undergone PTCH1 and SUFU testing on peripheral blood DNA, with no reportable variants identified." (PMID 41888819, 2026). "Shh signaling, driven exclusively by PTCH1 that is SMO/GLI1-independent, includes induction of apoptosis in endothelial and neuroepithelial cells and regulation of the Cyclin B1/CDK1 pathway in basal cell carcinoma." (PMID 26545965, 2015). "In conclusion, the proposed genetic variants (rs357564, rs2236405, rs2297086, and rs41313327) of the PTCH1 gene may not be involved in basal cell carcinoma development in the western Mexico population." (PMID 38287479, 2024). "Also, a nuclear localization of SMO, which drives GLI1 activation and is unresponsive to SMO inhibitors, has been reported to occur in Ptch1-silenced Basal Cell Carcinoma cells, again suggesting the activity of alternative non-canonical Hh-signaling." (PMID 31873117, 2019). "Ptch1 heterozygotes, which is a transmembrane receptor of Shh ligand as repressor of SHH signaling, are hypersensitive to ionizing radiation induced tumorigenesis and may develop tumors such as basal cell carcinoma." (PMID 23762282, 2013).
breast carcinoma (47 papers, 2008 to 2026). "As a protein found on the cell surface and the Golgi apparatus, it functions as a tumor suppressor, and mutations of the PTCH1 gene have been associated with poor prognosis and increased recurrence of breast cancer." (PMID 35033985, 2022). "PTCH1 mutations have also been reported in breast cancer patients, which were associated with poor prognosis and increased tumor recurrence rate." (PMID 34572373, 2021). "The multiplicity of PTCH1 tumor-suppressive functions supports PTCH1 mutations as a strong predictor of breast cancer recurrence meriting further study." (PMID 32957513, 2020). "The patients with mutated PTCH1 had a high risk of metastasis in the lung, liver, or distant lymph nodes and a decreased number of TILs in breast cancer samples." (PMID 31704974, 2019). "Our findings suggest that mutation of PTCH1 is correlated with early recurrence of breast cancer patients and will become a powerful predictor for recurrence of breast cancer." (PMID 31704974, 2019). "A combination of public databases of online information and targeted deep sequencing of 44 breast cancer patients in National Cheng Kung University Hospital identified PTCH1 mutations in the present study." (PMID 31704974, 2019). "Remarkably, we found a high mutation rate of PTCH1 in Taiwanese breast cancer patients (3.70% in our series vs. 0.91% in COSMIC, or 1.39% in TCGA)." (PMID 31704974, 2019). "Decreased amounts of tumor-infiltrating lymphocytes (TILs) were detected in breast cancer samples with mutated PTCH1 (21% low TILs in mutated PTCH1 vs. 79% low TILs in wild-type)." (PMID 31704974, 2019). "A recent report suggested loss of PTCH1 in 19% of human breast cancers, and 33% of breast cancer cell lines." (PMID 18990233, 2008). "Furthermore, mutated PTCH1 was proposed as a strong predictor of recurrence in breast cancer, and fusion of PTCH1 with glioma-associated proteins was associated with oncogenic activation in different tumors." (PMID 37700842, 2023). "However, it was found that patients with breast cancer and PTCH1 mutation had more metastasis in the lungs and worse recurrence-free survival." (PMID 35982978, 2022). "However, PTCH1 had particularly low CNVs but a surprisingly high mutation rate in these breast cancer patients." (PMID 31704974, 2019). "The clinical importance of PTCH1 mutations in breast cancer is implicated." (PMID 31704974, 2019). "Exons 22 and 23 encode potentially crucial segments for PTCH1 protein in breast cancer." (PMID 31704974, 2019). "The biallelic variant c.3944T of the PTCH1 gene is significantly associated with breast carcinoma." (PMID 27825128, 2016). "Ptch-1 mutations were identified in a small proportion of breast cancers at that time." (PMID 26389956, 2015). "However, biallelic Pro1315Leu (C3944 T) PTCH1 polymorphism was found associated with breast cancer risk when combined with oral contraception." (PMID 25503972, 2014). "Loss of heterozygosity of the PTCH1 gene is found in 30% of breast cancer patients." (PMID 25503972, 2014). "In the present study, we demonstrate the presence of PTCH1 mRNA in tumour samples and circulating tumour cells from breast cancer patients, particularly those with triple-negative breast cancer (TNBC)." (PMID 42001685, 2026). "Mechanistically, Tspan8 enhances breast cancer cell stemness by interacting with PTCH1, recruiting ATXN3 deubiquitinating enzymes to inhibit proteasome-mediated degradation of the SHH/PTCH1 complex, and activating the Hedgehog signaling pathway." (PMID 38649381, 2024). "Our results strongly suggest that PTCH1 and CTNNB1 can be used as robust and cost-effective predictors in developing countries to guide decisions on chemotherapy in ER +/HER2- breast cancer patients with a high risk of recurrence." (PMID 37700842, 2023). "In addition, PTCH1 gene mutation or autoantibodies to PTCH1 could be predictors of breast cancer." (PMID 36835134, 2023).